COMP (cartilage oligomeric matrix protein)
Diseases named in the same sentence as COMP in open-access papers (continued):
Sharing a sentence is not in itself a finding about the gene and the disease.
cancer (continued). "Moreover, significant correlations were found between COMP expression and the expression of immune checkpoint genes in most cancers." (PMID 36551305, 2022). "High COMP expression renders cancer cells resistant to apoptosis induction and endoplasmic reticulum stress and enhances the Warburg effect, which may be attributed to the prevention of Ca2+ release from ER." (PMID 36012514, 2022). "Beyond a prognostic biomarker, increased COMP (free in serum or derived by exosome) in circulation may target remote tissues and organs, including cancer, to modify their functions and make them to be more “stem cell-like” or “activated”." (PMID 36012514, 2022). "Moreover, COMP has been found in several cancer types in which it is expressed by epithelial cancer cells and in the surrounding matrix." (PMID 34884987, 2021). "However, the roles of COMP in the development and progression of cancer as well as the mechanisms involved in these processes have not been fully clarified." (PMID 33613749, 2021). "The liver, lymph nodes, and other collagen-rich tissues could be providing COMP-expressing cancer cells a better locus for metastases." (PMID 34884987, 2021). "Comparisons of the S-COMP levels and COMP levels that were detected using immunohistochemistry (IHC expression) in cancer cells and stroma in distant metastases (DM) revealed a positive correlation of high S-COMP levels in patients that had a strong IHC COMP expression in DM stroma (p = 0.01)." (PMID 34884987, 2021). "COMP, encoding a non-collagenous extracellular matrix protein, is up-regulated in various cancers and involved in cancer cell proliferation, tumorigenesis, epithelial-mesenchymal transition, and stemness features." (PMID 32850407, 2020). "However, little is known about the regulatory mechanism of COMP expression and its role in maintaining cancer stem-like phenotypes." (PMID 30999932, 2019). "The rest 25 genes including CENPI, COMP and TROAP may be novel cancer-associated genes that are worthy of validation in further studies." (PMID 28489584, 2017). "COMP expression was apparent in the cytosol of cancer cells but also in surrounding fibroblasts." (PMID 29228690, 2017). "Inhibition of COMP may thus be a promising therapeutic target in cancer treatments." (PMID 41009743, 2025). "Nonetheless, these differences were seen starting at 8 weeks post-cancer injection in their immunocompromised model, which may limit their findings, as COMP is known to also affect cancer cell binding with complement and the various immune pathways thereafter stimulated." (PMID 38892202, 2024). "Consequently, we hypothesized that COMP, when localized intracellularly in the ER, rescues cancer cells from apoptosis." (PMID 38965233, 2024). "Of a total 626 samples, COMP staining of cancer cells could be evaluated in 536 samples and in the stroma in 537 samples, due to tissue detachment distributed randomly between the slides, or because cancer cells or stroma were not present in some samples (2 samples)." (PMID 37207219, 2023). "One may hypothesize that COMP expression in LNM contributes to the development of distant metastases either by affecting the intravasation of the cancer cells to the bloodstream or the lymphatic system or by providing an advantage to the cancer cells to spread to collagen-rich metastatic locus." (PMID 34884987, 2021). "In addition, COMP initiates cancer stem cells by activating Jagged1-Notch3 signaling." (PMID 32754278, 2020). "Therefore, metastatic cancer cells that express COMP may be attaching more strongly to the bone tissue, fit better to the local microenvironment of the tissue and thus proliferate and survive better in this niche." (PMID 31737569, 2019).
cancer (continued). "Notch3 is activated when it binds to its ligand Jagged1, and COMP can bind both molecules (Notch3 and Jagged1) and increase their interaction, leading to a higher activation of the Notch pathway and cross-talking with other important cancer related molecular pathways, such as AKT and β-catenin." (PMID 31737569, 2019). "COMP binds to CD36, CD47, and avβ3 and avβ5 integrins, activating the Src and PI3k/AKT pathways, which promote cancer cell proliferation, invasion and metastasis." (PMID 41009743, 2025). "Mechanistically, the membrane-bound COMP induced EMT and cancer stemness via the activation of the Notch3 axis." (PMID 38615020, 2024). "Further, COMP expression correlates with exclusion of several types of immune cells including CD8+ T-cells and NK cells from the cancer cell compartment, by a mechanism that is potentially independent of PD-L1 expression." (PMID 37207219, 2023). "Compared with expression in adjacent tissues, the expression of COMP and SERPINB3 is all upregulated in cancer tissues." (PMID 37965307, 2023). "We then aimed to investigate the prognostic value of COMP expression levels in CRC tumors corrected for PD-L1 expression by immune cells and cancer cells, and the different markers of immune cells populations (CD3+, CD8+, FoxP3+, CD68+, CD56+, and CD163+)." (PMID 37207219, 2023). "Previous studies have elucidated the pivotal role of cartilage oligomeric matrix protein (COMP), also known as thrombospondin-5 (TSP-5), in various cancers." (PMID 37838792, 2023). "The expressions of BGN, COMP, COL5A2, and SPARC were further verified using scRNA-seq data between cancer and normal samples." (PMID 34899080, 2021). "In conclusion, COMP is upregulated in PTC, which increases cancer cell invasion and inhibits apoptosis, thus contributing to the development and progression of PTC." (PMID 33613749, 2021). "Kaplan–Meier survival analysis showed that the expression levels of COL1A1, COMP, and SERPINE2 significantly correlated with cancer-specific survival and overall survival of BC patients." (PMID 32850407, 2020). "For these reasons, the purpose of this study was to evaluate a new non-invasive way for the detection of COMP expression in tumors, utilizing an IVD approved ELISA that can evaluate the levels of COMP in sera of cancer patients." (PMID 31737569, 2019). "Our results indicated that RvD1 impaired paracrine of CAFs-derived COMP by targeting FPR2/ROS/FOXM1 signaling to repress EMT and cancer stemness in HCC." (PMID 30999932, 2019). "In this study, we mainly concentrated on the upstream mechanism by which RvD1 provided paracrine inhibition of CAFs-derived COMP via FPR2/ROS/FOXM1 cascades to prevent EMT and cancer stemness in HCC." (PMID 30999932, 2019). "Expression of COMP was not correlated with the expression of PD-L1 by the cancer cells or immune cells." (PMID 38563861, 2024). "For patients with right colon primary tumors, we found a negative correlation between the PD-L1-expressing cancer cells and the levels of COMP in the stroma." (PMID 37207219, 2023). "High levels of COMP expression in the stroma, but not in cancer cells, were correlated with collagen fiber density and the number of branch points." (PMID 37207219, 2023). "Although it has been shown that COMP promotes cancer-cell proliferation via activation of the PI3K/Akt/mTOR/p70S6K signaling pathway, more studies are required to decipher the role of this protein in cancer progression and metastasis." (PMID 36765749, 2023). "Further, the available data did not allow us to study the mechanism by which COMP expression is triggered during cancer development, which will be interesting to address in the future." (PMID 37207219, 2023).
cancer (continued). "We demonstrated that COMP enhanced the invasion of PTC cells, inhibited their apoptosis, and altered their cellular metabolism, making them resistant to death, which are important characteristics of cancer cells." (PMID 33613749, 2021). "Several genes, such as EGFL6 (EGF Like Domain Multiple 6), COMP (Cartilage Oligomeric Matrix Protein), and SULF1 (Sulfatase 1), have been found to be related to multiple terms, and they are all research-proven cancer-related biomarkers." (PMID 35178071, 2021). "Furthermore, RvD1 inhibited CAFs-induced cancer stemness and EMT in HCC cells by suppressing the secretion of COMP." (PMID 30999932, 2019). "Interestingly, herein we found that RvD1 inhibited COMP in CAFs in a paracrine manner to modulate EMT and cancer stemness in HCC, providing a promising therapeutic strategy for patients with HCC." (PMID 30999932, 2019). "Patients with tumors expressing COMP in cancer cells had a median OS of 1.2 years compared with 2.6 years for patients with tumors lacking COMP expression in cancer cells (p = 0.013), and the corresponding figures for RFS were 1.1 years and 2.1 years, respectively (p = 0.029)." (PMID 38563861, 2024). "Also, the same authors reported that DU145 cancer invasion into tissues was dependent on the Src and integrin pathway and not on those involving PI3K, JAK-2, NFkB, and RAC, as the cells that were transfected with COMP invaded more than those mock-transfected." (PMID 38892202, 2024). "In contrast, COMP expression by cancer cells was not correlated with MSI." (PMID 37207219, 2023). "Interestingly, in one of these studies COMP has been predicted to be expressed by the cancer cells rather than the stromal cells." (PMID 34884987, 2021). "Similarly, a trend for a positive correlation was seen between patients with high S-COMP levels and IHC COMP expression in DM cancer cells, however this was not significant (p = 0.13)." (PMID 34884987, 2021). "Therefore, COMP and TAGLN are promising new targets for the treatment of malignant tumors." (PMID 32754278, 2020). "COMP encodes noncollagenous ECM profiles and might promote EMT in cancer cells." (PMID 38203315, 2023). "COMP expression was evaluated in 159 of 174 samples, as the omitted TMA cores had been detached or lacked cancer cells or stroma." (PMID 38563861, 2024).
skeletal dysplasia (21 papers, 2005 to 2025). Any Mendelian diseases that affects growth and development of the skeleton. "Autosomal dominant missense and in-frame insertion/deletion mutations in the COMP gene cause two forms of skeletal dysplasia: pseudoachondroplasia and multiple-epiphyseal dysplasia." (PMID 39672391, 2025). "The crucial role of COMP in the structure and function of the musculoskeletal system is confirmed by the development of skeletal dysplasias in COMP gene mutations." (PMID 38791302, 2024). "Patient #144 carried a heterozygous mutation in COMP (c.949G > T) and presented with short stature accompanied by skeletal dysplasia." (PMID 37605180, 2023). "Disease-associated variants in COMP cause impaired cartilage development leading to skeletal abnormalities such as short stature and skeletal dysplasias." (PMID 36561048, 2022). "While mutations of Thbs5, better known as cartilage-oligomeric matrix protein (Comp), cause two different forms of skeletal dysplasia, the role of Thbs3 and Thbs4 in the skeleton are still poorly defined." (PMID 26629997, 2015). "Mutations in the Ca2+-binding region of COMP lead to skeletal dysplasia." (PMID 33227073, 2020). "This suggests that reducing mutant and wild-type COMP expression in chondrocytes may prevent the toxic cellular phenotype causing the skeletal dysplasias." (PMID 20421976, 2010). "A notable aspect of this study was the frequency of heterozygous mutations detected in genes previously associated with skeletal dysplasia (NPR2, ACAN, CASR, COMP, and FBN1), confirming the dose effect of cartilage matrix proteins in growth and development." (PMID 37605180, 2023). "Some of these newly identified genes are well characterized as cartilage-selective and associated with one of a variety of forms of skeletal dysplasia (e.g., TRPV4, COL2A1, COMP, and COL9A3)." (PMID 20046828, 2009). "One novel COMP pathogenic variant c.1359delC, p.N453fs*62 and one LZTR1 likely pathogenic variant c.509G>A, p.R170Q were identified in a patient with short stature and skeletal dysplasia." (PMID 39415983, 2024). "It is the disparity between the human PSACH phenotype and COMP null mouse phenotype that led us to investigate RNAi as a potential therapy for COMP-related skeletal dysplasias by eliminating all COMP mRNA." (PMID 20421976, 2010). "Therefore, the molecular cell pathology of MED caused by MATN3 mutations has similarities to skeletal dysplasias caused by mutations in the genes encoding other extracellular matrix structural proteins, particularly PSACH and forms of MED that result from mutations in COMP [Unger and Hecht, 2001]." (PMID 16287128, 2005).
infection (12 papers, 2013 to 2025). The state of being infected such as from the introduction of a foreign agent such as serum, vaccine, antigenic substance or organism. "The infection of P. shigelloides is complex, and many virulence genes are involved, such as hemolysin, flagellin, elastase, enterotoxin, cholera-like toxins, cytotoxic outer membrane protein (comP), and the factors related to secretion system." (PMID 40301844, 2025). "Among these, the cytotoxic outer membrane protein ComP may be a major virulence factor responsible for host mortality after infection, while hemolysins, enterotoxins, and cholera-like toxins can cause varying degrees of damage to the host." (PMID 40301844, 2025). "Thus, our investigation is the first report about the roles of signaling system ComP-ComA in the infection of bacterial pathogens." (PMID 24130811, 2013).
myopathy (7 papers, 2010 to 2025). A disease of the muscle in which the muscle fibers do not function properly. "Shortly after the initial discovery of muscle abnormalities in EDM3, mild myopathy was also reported in EDM1 patients with CTD COMP mutations." (PMID 41155349, 2025). "In addition to the diagnostic challenge, clinically variable myopathy symptoms have also been observed in PSACH-MED patients, particularly those with mutations in genes encoding type IX collagen, COMP, and, more recently, matrilin-3." (PMID 41155349, 2025). "In addition to CTD mutations, although T3 mutant COMP is often retained in chondrocytes, it can be secreted in tendons and ligaments causing a myopathy." (PMID 41155349, 2025). "For example, COMP has been shown to bind to integrins, which are implicated with myopathy, suggesting that disrupting the ECM may contribute to the muscle pathologies observed in PSACH-MED." (PMID 41155349, 2025). "Further analysis of patients and mice models of PSACH-MED will help clarify the pathology and disease mechanisms of mild myopathy resulting from type IX collagen and COMP mutations." (PMID 20358595, 2010). "MED has been associated with mild myopathy in some families, in particular one family with a COL9A3 mutation and two families with C-terminal COMP mutations." (PMID 20358595, 2010). "Patients with COL9-related MED may exhibit myopathy findings similar to those seen in COMP-related MED." (PMID 40392407, 2025). "MED-related myopathy has been reported in some families with COL9A3, COMP, and COL9A2 mutations." (PMID 25381065, 2014). "We conclude that the PSACH/MED related mild myopathy correlates predominantly with COMP mutations but not a matrilin-3 mutation." (PMID 24312420, 2013). "Therefore, this highlights that muscle weakness and myopathy are associated with type IX collagen and COMP mutations but not with matrilin-3 mutations." (PMID 41155349, 2025). "In addition to CTD COMP mutations, T3 COMP mutations have also been associated with mild myopathy, suggesting that the muscular complications are COMP mutation-specific and not domain-specific." (PMID 41155349, 2025). "However, patients with these diseases (predominantly those with COMP and type IX collagen gene mutations) are occasionally referred to neuromuscular clinics with symptoms of a ‘non-defined’ mild myopathy before being correctly diagnosed with chondrodysplasia." (PMID 24312420, 2013). "Notably, not all CTD and T3 COMP mutations cause myopathy, prompting the suggestion that the muscle pathology may be linked to the proximity of the mutation to potential bindings sites within COMP." (PMID 41155349, 2025).
cardiovascular diseases (6 papers, 2018 to 2025). "Targeting COMP in malignancy may withdraw its beneficial effects on the vascular system and induce or aggravate cardiovascular diseases." (PMID 36012514, 2022). "Increasing endogenous COMP or improving mitochondrial respiration may help maintain the VSMC contractile phenotype to inhibit several cardiovascular diseases." (PMID 29867124, 2018).
musculoskeletal disease (3 papers, 2008 to 2025). "COMP has been studied intensively due to the fact that COMP mutations are associated with musculoskeletal disease." (PMID 19014566, 2008). "Studies with musculoskeletal disease models in rabbits revealed several pathognomonic serum biomarkers, such as C-telopeptide of type II collagen, bone morphogenic protein 2, and cartilage oligomeric matrix protein." (PMID 40654513, 2025).
connective tissue diseases (2 papers, 2017 to 2022). "Despite its principal associations with connective tissue diseases, mounting evidence suggests a clinically relevant role for COMP in fibrogenesis within multiple organ systems." (PMID 28114331, 2017). "These children might be the carrier to the connective tissue disorder due to defective extracellular matrix as seen with COMP, COL2A1, COL9A1, COL9A2, etc. genetic mutation." (PMID 33870477, 2022). "COMP has been well described in skeletal and connective tissue disorders, including pseudoachrondroplasia and osteochrondroplasias." (PMID 28114331, 2017).
autosomal dominant disease (1 paper, 2021). Autosomal dominant form of disease. "PSACH is an autosomal dominant disease that is considered to result from mutations in the gene encoding the cartilage oligomeric matrix protein (COMP)." (PMID 33748277, 2021).
intestinal disease (1 paper, 2017). "Together with these emerging methods, COMP and HGFA could aid in non-invasively determining the histologic composition of intestinal disease." (PMID 28114331, 2017).
osteoarthropathy (1 paper, 2022). "This was also the main reason why rhGH is not recommended for patients with COMP mutations leading to PSACH, usually accompanied by severe osteoarthropathy." (PMID 35250876, 2022).
COMP also shares sentences with these, for which no sentence is quoted: intervertebral disc degeneration (4 papers); degenerative diseases (3); juvenile idiopathic arthritis (3); liver disease (3); metaphyseal chondrodysplasia type Schmid (3); renal fibrosis (3); rheumatic diseases (3); type II collagenopathies (3); adenocarcinoma (2); anemia (2); ankylosing spondylitis (2); biliary atresia (2); chronic viral hepatitis (2); colon adenocarcinoma (2); familial carpal tunnel syndrome (2); gastrointestinal tumors (2); hip osteoarthritis (2); lung adenocarcinoma (2); Nephropathy (2); neutropenia (2); osteogenesis imperfecta (2); papillary thyroid carcinoma (2); short limbed dwarfism (2); Skeletal Diseases (2); Thrombocytopenia (2); type 2 diabetes (2); acromelic dysplasia (1); alcohol abuse (1); amyotrophic lateral sclerosis (1); aneurysm (1).
A further 61 diseases each share a sentence with COMP in 1 paper.